TRIM21 (tripartite motif containing 21)
Diseases named in the same sentence as TRIM21 in open-access papers (continued):
Sharing a sentence is not in itself a finding about the gene and the disease.
lymphoma (9 papers, 2008 to 2026). A malignant (clonal) proliferation of B- lymphocytes or T- lymphocytes which involves the lymph nodes, bone marrow and/or extranodal sites. "TRIM21/Ro52 deficiency may be relevant to the increased risk of lymphoma because of NF‐κB pathway activation, and maintaining TRIM21 expression is also associated with a preferable clinical outcome in patients with lymphoma." (PMID 37993883, 2023).
rheumatic diseases (9 papers, 2020 to 2026). "The Ro52 protein, also known as TRIM21, is frequently targeted by SS antibodies, which makes it a useful diagnostic marker, but its function and why it becomes a target protein in a lot of rheumatic diseases is not completely understood." (PMID 32698400, 2020).
anemia (8 papers, 2019 to 2025). A reduction in the number of red blood cells, the amount of hemoglobin, and/or the volume of packed red blood cells. "A previous study demonstrated anti-Ro52/TRIM21 was associated with anaemia in patients with SS." (PMID 35871174, 2022). "Surprisingly, we found higher proportions of patients with anaemia in the isolated anti-Ro52/TRIM21 group." (PMID 35871174, 2022). "Moreover, isolated anti-Ro52/TRIM21 had higher rates of anaemia." (PMID 35871174, 2022).
renal carcinoma (8 papers, 2023 to 2025). A carcinoma arising from the epithelium of the renal parenchyma or the renal pelvis. "On the other hand, TRIM21 could inhibit glycolysis of renal cancer cells by degrading HIF-1α to hinder tumor progression." (PMID 40998798, 2025). "Previous research has demonstrated that TRIM21 can facilitate HIF‐1α ubiquitination, leading to attenuation of renal cancer progression." (PMID 39556022, 2024). "Additional investigation uncovered that TRIM21 hindered cell proliferation and metastasis by facilitating the breakdown of HIF-1α, hence suppressing cell glycolysis in renal cancer cells." (PMID 38773612, 2024). "Here, we discovered that TRIM21 inhibits lipid accumulation in RCC cells and prevents renal carcinoma tumorigenesis." (PMID 36694250, 2023). "Here, we found that TRIM21 inhibits lipid accumulation in RCC cells and prevents renal cancer tumorigenesis." (PMID 36694250, 2023). "TRIM21, a E3 ligase, interacts with SREBF1 through its SPRY domain and mediates its ubiquitination and degradation via K63 linkage, suppressing lipid metabolism in renal cancer." (PMID 39944823, 2025).
adenovirus infection (7 papers, 2012 to 2023). "Consistent with complement and TRIM21 being antibody-dependent neutralization mechanisms, patients with agammaglobulinemia are more susceptible to adenovirus infections, which can be severe or even fatal." (PMID 30926239, 2019). "The recently reported mechanism of intracellular immunity mediated by Ro52/TRIM21 in a cellular model of adenovirus infection has opened new perspectives for studying the effects of autoantibodies once they are inside cells." (PMID 22394602, 2012). "Strikingly, the inflammatory/fibrotic response was also induced by TRIM21 silencing, likely because of the elevated steatosis, which may suggest TRIM21-independent elevation of inflammation resulted by the adenovirus infection or via other unknown mechanisms." (PMID 37937648, 2023). "Whether adenovirus infections in the eye may benefit from TRIM21 and antibody therapy remains to be addressed, however, injection of antibodies into the vitreous is frequently used in the clinic to treat eye diseases such as age-related macular edema." (PMID 31555278, 2019). "Interestingly, we noted that adenoviral TRIM21 overexpression attenuated lipogenic liver injury, as evidenced by the decreased ALT and AST levels in db/db mice in comparison with control adenovirus infection in those mice." (PMID 37249651, 2023). "The different results may be because the requirement for Ube2W-mediated TRIM21 RING autoubiquitnation is adenovirus-specific, although the ability of an N-terminally acetylated R-R-PS to neutralize adenovirus infection even more efficiently than a non-acetylated equivalent argues against this." (PMID 37061529, 2023).
esophageal squamous cell carcinoma (7 papers, 2011 to 2025). Esophageal squamous cell carcinoma (ESCC) is a type of esophageal carcinoma (EC) that can affect any part of the esophagus, but is usually located in the upper or middle third. "In patients with esophageal squamous-cell carcinoma, anti-TRIM21 Abs have been linked to poor survival, whereas in those with ovarian cancer, a high prevalence of these Abs has been associated with improved OS." (PMID 40768895, 2025). "Anti-TRIM21/Ro52 positive is associated with poor survival in patients with esophageal squamous cell carcinoma." (PMID 37993883, 2023).
lung disease (7 papers, 2012 to 2024). "Interestingly, the authors reported that the prevalence of pulmonary disease was particularly high among anti-Ro52/TRIM21 antibody-positive patients (22% of patients), including seven of 11 patients with SSc." (PMID 22394602, 2012). "Interestingly, it was found that the probability of concurrent lung disease was relatively high among anti-TRIM21 positive patients relative to anti-TRIM21 negative patients, and there was an association with concurrent ILD." (PMID 39165359, 2024).
cervical carcinoma (6 papers, 2020 to 2025). A carcinoma arising from either the exocervical squamous epithelium or the endocervical glandular epithelium. "To determine whether the RING domain of the TRIM21 protein mediates the degradation of NCAPH in cervical cancer, we transfected HeLa and SiHa cells with a full-length TRIM21 plasmid (HA-TRIM21) and a RING domain-mutated plasmid (TRIM21 ΔRING)." (PMID 39103348, 2024). "We inhibited the expression of TRIM21 in cervical cancer cells and performed a colony formation assay with or without RAPA treatment." (PMID 39103348, 2024). "With the reduction in TRIM21 expression, the colony formation capacity of cervical cancer cells increased significantly, and with the addition of RAPA, it decreased dramatically." (PMID 39103348, 2024). "To further clarify the specific site at which NCAPH is modified by TRIM21, we added a specific site, the ubiquitin chain, to cells cocultured with cervical cancer cells." (PMID 39103348, 2024). "The HPV E7 oncoprotein has been described to activate the TRIM21-mediated proteasomal degradation of gamma-interferon-inducible protein-16 (IFI16) in cervical cancer cell lines." (PMID 36982215, 2023). "In our study, we elucidated that TRIM21 could inhibit autophagy by regulating the expression of NCAPH in cervical cancer cells." (PMID 39103348, 2024). "Therefore, TRIM21 promoted autophagy in cervical cancer by inhibiting NCAPH and the downstream AKT/mTOR pathway." (PMID 39103348, 2024). "To further confirm these results, we performed immunohistochemical staining and found that TRIM21 was overexpressed in 129 patients with cervical cancer (129/220, 58.64%), NCAPH was overexpressed in 84 patients (84/220, 38.18%), and beclin-1 was overexpressed in 156 patients (156/220, 70.91%)." (PMID 39103348, 2024). "Here, we found that NCAPH was a novel target protein of the E3 ligase TRIM21 in cervical cancer." (PMID 39103348, 2024). "Therefore, we provide evidence for the role of the TRIM21-NCAPH axis in cervical cancer autophagy and proliferation and the involvement of the AKT/mTOR signaling pathway in this process." (PMID 39103348, 2024). "Our data demonstrated a novel molecular pathway in cervical cancer, that is, TRIM21 degrades NCAPH through K-11 ubiquitination, thus inhibiting the activation of the downstream AKT/mTOR pathway, promoting autophagosome formation and inhibiting cell proliferation." (PMID 39103348, 2024). "Therefore, the future development of TRIM21-targeting agonists is expected to significantly inhibit cervical cancer growth." (PMID 39103348, 2024). "Moreover, TRIM21 degrades anti-apoptotic molecule, Bcl2, thereby triggering apoptosis in cervical cancer cells." (PMID 32678213, 2020). "Consistent with in vitro findings, TRIM21 expression was negatively correlated with that of NCAPH, but positively with Beclin-1 in cervical cancer patients." (PMID 39103348, 2024). "Immunohistochemical staining revealed that the protein expression of TRIM21 was negatively correlated with that of NCAPH and positively correlated with that of beclin-1 in cervical cancer tissues." (PMID 39103348, 2024). "To further verify the correlation between TRIM21, NCAPH and autophagy, we performed a bioinformatics analysis in cervical cancer." (PMID 39103348, 2024). "However, it is unknown whether TRIM21 can regulate the AKT/mTOR pathway in cervical cancer." (PMID 39103348, 2024). "The PRY/SPRY domain of TRIM21 interacts with γ-interferon-inducible protein-16 (IFI16) and mediates the degradation of IFI16 in a K33-linked manner, leading to the inhibition of cell pyroptosis and self-escape from immune surveillance, which may account for the occurrence of cervical cancer." (PMID 36159815, 2022). "Furthermore, TRIM21 promoted autophagosome formation and reduced cell proliferation by inhibiting NCAPH expression and the downstream AKT/mTOR pathway in cervical cancer cells." (PMID 39103348, 2024).
cervical carcinoma (continued). "Furthermore, TRIM21 inhibited cell proliferation by hindering NCAPH-mediated activation of the AKT/mTOR pathway and autophagosome formation in cervical cancer." (PMID 39103348, 2024).
liver diseases (6 papers, 2013 to 2025). "Hepatitis B virus (HBV) infection is a major contributor to liver diseases; however, the host factors regulated by cytokine-inducible TRIM21 to suppress HBV remain unclear." (PMID 38780244, 2024). "We investigated whether metabolic stress conditions and liver disease states affect the expression of TRIM21." (PMID 37937648, 2023).
ovarian carcinoma (6 papers, 2019 to 2025). A malignant neoplasm originating from the surface ovarian epithelium. "Similarly, colitis-associated and ovarian cancer studies indicate that TRIM21/Ro52 can suppress intestinal epithelial carcinogenesis and ovarian tumorigenesis, respectively." (PMID 37993883, 2023). "In another study, although there was a significantly high prevalence of anti-TRIM21/Ro52 in ovarian cancer patients, the presence of this antibody was correlated with higher overall survival compared with the antibody-negative ovarian cancer population." (PMID 37993883, 2023).
colitis (5 papers, 2023 to 2025). Inflammation of the colon. "Inhibiting the ubiquitination of TRIM21 and the degradation of IRF3 in colitis induced by TRIM21-/-mice caused an increase in IL-17+CD4+ and IFN-γ+CD4+T cells, accompanied by an intensified immune reaction from CD4+T cells, culminating in heightened inflammation of the intestinal mucosa." (PMID 39165359, 2024). "Additionally, TRIM21 expression was found to be reduced in cancers associated with colitis and to negatively regulate intestinal epithelial carcinogenesis by modulating epithelial cell proliferation, adhesion, tissue remodeling, and angiogenesis as well as pro-inflammatory responses." (PMID 37653392, 2023). "In CD4+T cells, TRIM21 degraded multiple metabolic enzymes in a proteasome-dependent manner to alleviate the onset of T cell-mediated colitis." (PMID 37249651, 2023). "SIRT5 deacetylates Lys351 of TRIM21, inhibiting the production of IL-1β and preventing colitis." (PMID 39979670, 2025). "Lipopolysaccharide-induced polarization of pro-inflammatory macrophages biases tripartite-motif protein (TRIM21)-SIRT5 interactions toward activation of TRIM21 and degradation of SIRT5, leading to increased interleukin-1beta (IL-1β) production in vitro and in vivo, thereby aggravating colitis." (PMID 39979670, 2025).
diabetes (5 papers, 2021 to 2024). "The identification of FOXD1 as a critical transcription factor for BCL-2 in the retina and kidney and the TRIM21-mediated regulation of FOXD1 stability complement our findings regarding therapeutic strategies for diabetes mellitus." (PMID 38092733, 2023). "In the current study, we identify E3 ligase TRIM21 as a novel player in hepatic glycolipid metabolism abnormalities that leads to the development and progression of type 2 diabetes mellitus." (PMID 37249651, 2023). "Since hepatic steatosis has been regarded as a driving force for insulin resistance and type 2 diabetes mellitus, the improved insulin sensitivity by TRIM21 could ameliorate hepatic glucose and lipid metabolic disorders by ubiquitination of FASN expression." (PMID 37249651, 2023). "Furthermore, genomic data from an NCBI GEO database shows that TRIM21 mRNA level is decreased in the blood of type 2 diabetes mellitus patients (GEO, accession number GSE26168)." (PMID 37249651, 2023). "Our results suggest that TRIM21 is a crucial suppressor of hepatic glucose and lipid metabolism disorders and insulin resistance and thus may serve as a molecular target for treating type 2 diabetes mellitus." (PMID 37249651, 2023). "It is known that TRIM21 is expressed in numerous organs, however, the relative importance of organ-specific TRIM21 in type 2 diabetes mellitus has not been investigated." (PMID 37249651, 2023). "Similarly, the increase in the expression of TRIM21 triggered by high-glucose exposure was not affected by diabetes-related AGEs and ROS, as demonstrated through the use of the inhibitors FPS-ZM1 (RAGE) and setanaxib (ROS)." (PMID 38092733, 2023).
lung carcinoma (5 papers, 2016 to 2024). "TRIB2 has previously been shown to function as an adaptor mediating the degradation of C/EBPα via COP1 E3 ligase in AML or TRIM21 E3 ligase in lung cancer, and these are likely candidates that link the TRIB2 pseudokinase domain to ubiquitination." (PMID 27563873, 2016). "Dihydroartemisinin treatment enhances radiation sensitivity and displays an inverse correlation by reducing PD-L1 levels and elevating TRIM21 expression, suggesting a potential pathway for overcoming radiation resistance in lung cancer cells by targeting the PD-L1/TRIM21 axis." (PMID 38474186, 2024). "However, we did not observe similar correlation between the protein expression of SIRT5 and SUCLG2, like that between TRIM21 and SUCLG2, in lung cancer tissues and adjacent normal tissues." (PMID 37904651, 2023).
lymphopenia (5 papers, 2013 to 2025). Reduction in the number of lymphocytes. "Among the different lymphocyte subsets, evidence exists that CD4+ and NK cells are involved in the lymphopenia associated with anti-Ro or, specifically, with anti-Ro52/TRIM21." (PMID 24294139, 2013). "Thus, anti-Ro52/TRIM21 was found to be significantly associated with lymphopenia, independently of the therapeutic regime, whereas patients with anti-SSA/Ro60 antibodies showed higher platelet numbers and lower haemoglobin levels than negative patients." (PMID 24294139, 2013). "Moreover, the association between anti-Ro52/TRIM21 and lymphopenia was further confirmed by logistic regression adjusted for sex, age, and treatment at time of analysis (OR 2.72, 95% CI 1.08–6.88, P = 0.035)." (PMID 24294139, 2013). "Our findings support the specific relationship of anti-Ro52/TRIM21 with lymphopenia in SLE described in previous works." (PMID 24294139, 2013). "Anti-SSA/Ro60 was found to be positively associated with hypocomplementemia but negatively with antiphospholipid antibodies, whereas anti-Ro52/TRIM21 showed a positive association with lymphopenia and Raynaud's phenomenon and a negative relationship with anti-dsDNA antibodies." (PMID 24294139, 2013).
multiple myeloma (5 papers, 2008 to 2025). "Another study reported that PRMT5 interaction with tripartite motif-containing protein 21 (TRIM21), an IKKβ ubiquitin ligase, inhibits IKKβ degradation in multiple myeloma, thereby inducing NF-κB signaling and cell growth of multiple myeloma cells." (PMID 34685445, 2021). "Consistent with this, a recent study also presented evidence that PRMT5 may functionally interact with TRIM21 in myeloma cells." (PMID 32023548, 2020). "For example, TRIM21 is involved in degradation of cyclin-dependent kinase 2 (CDK2) and ATG5 in AML and multiple myeloma cells." (PMID 40371639, 2025).
myocardial infarction (5 papers, 2019 to 2025). Gross necrosis of the myocardium, as a result of interruption of the blood supply to the area, as in coronary thrombosis. "Negative regulation of Nrf2-antioxidant axis is a common mechanism in TRIM21-mediated heart diseases, and has been verified in TAC-induced cardiac hypertrophy 22, doxorubicin-induced cardiotoxicity 23, and myocardial infarction-induced atrial remodeling." (PMID 39431010, 2024).
renal cell carcinoma (5 papers, 2020 to 2025). "The expression of TRIM21 was significantly reduced in renal cell carcinoma, and this decreased expression was linked to unfavorable clinicopathological features and decreased overall survival in RCC patients." (PMID 38773612, 2024). "In renal cell carcinoma, TRIM21 mediates ubiquitination-mediated degradation of sterol regulatory element binding transcription factor 1 (SREBF1) to inhibit the expression of lipogenic enzymes, thereby blocking lipogenesis and tumor development." (PMID 40735642, 2025). "In renal cell carcinoma, low TRIM21 expression was significantly positively correlated with tumor size, lymph node metastasis, and distant metastasis." (PMID 40735642, 2025). "In renal cell carcinoma, TRIM21 targets HIF-1α for ubiquitin-mediated degradation, thereby suppressing HIF-1α-dependent glycolytic programming in tumor cells." (PMID 40735642, 2025). "In addition, in renal cell carcinoma, overexpression of TRIM21/Ro52 destabilizes hypoxia-inducible factor 1 subunit alpha (HIF-1α), leading to the suppression of aerobic glycolysis and subsequent inhibition of both in vitro and in vivo tumor cell proliferation and migration." (PMID 37993883, 2023). "A recent study, in contrast, found that TRIM21/Ro52 inhibits the expression of the lipogenic enzyme via the degradation of sterol regulatory element binding transcription factor 1 (SREBF1), attenuating lipogenesis and tumor growth in renal cell carcinoma." (PMID 37993883, 2023).
thyroid cancer (5 papers, 2023 to 2025). "In thyroid cancer, higher TRIM21 expression is correlated with an increased risk of recurrences and lymph node metastases." (PMID 36982215, 2023). "TRIM21/Ro52 plays a similar role in thyroid cancer, such that the expression of TRIM21/Ro52 is upregulated in thyroid cancer tissue, and higher TRIM21/Ro52 levels are associated with a higher risk of recurrence and lymph node metastasis, though the mechanism involved has not yet been investigated." (PMID 37993883, 2023). "In terms of TRIM21 dysregulation, low TRIM21 expression was identified in KIRC (Kidney renal clear cell carcinoma), MESO (Mesothelioma), SARC (Sarcoma), SKCM (Skin Cutaneous Melanoma), READ (Rectum adenocarcinoma) and THCA (Thyroid carcinoma)." (PMID 37335642, 2023).
Alzheimer disease (4 papers, 2011 to 2024). A progressive, neurodegenerative disease characterized by loss of function and death of nerve cells in several areas of the brain leading to loss of cognitive function such as memory and language. "The low expression of TRIM21 manifested enrichment in the acute chemokine signaling pathway, whereas high expression TRIM21 was notably associated with Alzheimer's disease." (PMID 38965390, 2024).